COL5A1 (collagen type V alpha 1 chain)
Diseases named in the same sentence as COL5A1 in open-access papers (continued):
Sharing a sentence is not in itself a finding about the gene and the disease.
breast carcinoma (22 papers, 2017 to 2025). "At the protein level, the HPA database confirmed that the expression of COL5A1 in breast cancer was higher than that in normal tissues, which was consistent with the results of immunohistochemistry; moreover, the COL5A1 mutation was negatively correlated with the prognosis of breast cancer patients." (PMID 33281878, 2020). "COL1A1, COL1A2, COL11A1, and COL5A1 have been reported to regulate several cancers, including colorectal cancer, esophageal cancer, hepatocellular carcinoma, renal cell carcinoma, breast cancer, and gliomas." (PMID 38639039, 2024). "For instance, circACAP2 facilitates breast cancer growth and motility by regulating miR-29a/b and modulating COL5A1." (PMID 37303741, 2023). "Expression levels of the ECM structural proteins Col5A1 and Col15A1 significantly decreased while Col14A1 significantly increased in lung fibroblasts exposed to factors from metastatic breast cancer cells as compared to controls." (PMID 37903851, 2023). "COL5A1 (collagen type V alpha 1 chain) was found to be related to the occurrence and progression of multiple types of malignant tumors, including breast cancer and gliomas." (PMID 35800363, 2022). "The circACAP2 contributes to metastasis and proliferation of breast cancer by targeting miR-29a/b-3p-COL5A1 signaling." (PMID 35847361, 2022). "For example, in physiologic conditions, COL5A1 polymerizes with type I collagen to adjust collagen molecule diameter, with COL5A1 shown to be a potential biomarker for tumor progression in breast cancer." (PMID 34370182, 2022). "Upregulated COL5A1 indicated poor prognosis in breast cancer, clear cell renal cell carcinoma, lung adenocarcinoma and tongue squamous cell carcinoma 56-59." (PMID 33403045, 2021). "Notably, COL5A1 and COL6A1, among the identified markers, have been linked to CAF and are closely associated with the progression, invasion, and metastasis of breast cancer." (PMID 40226936, 2025). "The collagen family gene COL5A1 has been identified as a possible predictor of recurrence after radiation therapy for vestibular schwannoma (VS) and related to brain metastasis in breast cancer patients." (PMID 35631574, 2022). "circACAP2 promotes tumorigenesis in breast cancer by modulating the miR-29a/b-3p/COL5A1 axis." (PMID 33618745, 2021). "In addition, COL3A1, COL4A1, COL5A1, and COL15A1 are associated with immune infiltration in head and neck squamous cell carcinoma, breast cancer, mesothelioma, and other tumors." (PMID 34691289, 2021). "Recent studies have shown that COL5A1 is of high value in the prediction of breast cancer." (PMID 33281878, 2020). "Upon EZH2 knockdown, fold change in the target gene expression for GPNMB, CoL5A1, POMT2, PMEPA1, VGLL4 and SUMF1 was found to be 1.3, 2.8, 2.2, 2, 1.7 and 1.8, respectively in MCF-7 breast carcinoma cells as detected by qPCR." (PMID 30760814, 2019). "In addition to the major fibrillar collagen class, many minor fibrillar collagens, including those (COL11A1, COL5A1, and COL5A2) have reported prognostic value in breast cancer." (PMID 39716322, 2024). "When we further interrogated the expression of collagen genes commonly expressed in breast cancer ECM (COL1A1, COL1A2, COL3A1 and COL5A1) we observed decreased endogenous gene expression of these collagens in higher passage TU-BcX-4IC tumors compared to lower passage." (PMID 34370182, 2022). "Interestingly, another hub gene, COL5A1, as a target of EZH2, is upregulated by decreased activity of EZH2 in the breast carcinoma cell line." (PMID 35571032, 2022). "Finally, collagen type V alpha 1 (Col5a1) is mainly found in organ tissue together with collagen type I, a major ECM component of breast cancer." (PMID 29079737, 2017).
breast carcinoma (continued). "In a The Cancer Genome Atlas (TCGA) comparative study between normal breast tissue (n = 113) and breast tumors (n = 1109), COL11A1, COL12A1, COL1A1, COL1A2, COL5A1, and COL5A2 transcripts were upregulated in breast cancer and could discriminate between the two breast tissues." (PMID 39716322, 2024). "Here we provide preliminary evidence that COL5A1 expression is not necessary for tumor formation in our MBC model, suggesting this collagen may be specific for certain subtypes of breast cancer." (PMID 34370182, 2022).
keratoconus (19 papers, 2014 to 2026). A degenerative, structural disorder of the eye, characterized by a cone-shaped protrusion of the cornea. "The COL5A1 promoter (NC_000009.12: 134641188–134,642,551) was sequenced in a subgroup of keratoconus patients with at least one rs1536482 minor allele (n = 94)." (PMID 34625056, 2021). "We sequenced the COL5A1 promoter in a subgroup of keratoconus patients who had at least one rs1536482 minor allele." (PMID 34625056, 2021). "The rare variants rs1043208782 and rs569248712 were found in the COL5A1 promoter in two out of 94 rs1536482+ keratoconus patients." (PMID 34625056, 2021). "The presence of a TNXB or COL5A1 mutation (related to EDS) in a keratoconus patient might prompt screening for mitral valve prolapse or vessel fragility, for instance." (PMID 41595486, 2026). "The purpose of this study was to validate whether three reported keratoconus-associated SNPs (rs1536482 near the COL5A1 gene, rs2721051 near the FOXO1 gene, rs1324183 near the MPDZ gene) are also actual for a Russian cohort of patients." (PMID 34625056, 2021). "Additionally, we investigated rare variants in the COL5A1 promoter of keratoconus patients with at least one rs1536482 minor allele." (PMID 34625056, 2021). "VSX1 (Visual system homeobox 1), TIMP3, TGFBI, ZEB1, filaggrin (FLG) and several collagen genes, such as COL4A3, COL4A4 AND COL5A1, have been associated with keratoconus, while the distinct potential loci, which have been described, include 3p14-q13, 5q21, 5q32 and 14q11." (PMID 28932340, 2017). "Nevertheless, we present some data on the possible role of COL5A1 in the pathogenesis of keratoconus." (PMID 34625056, 2021). "We found that rs1536482 near the COL5A1 gene, rs2721051 near the FOXO1 gene, and rs1324183 near the MPDZ gene were significantly associated with keratoconus in a Russian cohort." (PMID 34625056, 2021). "The minor allele distribution was significantly different (p-value < 0.05) between the keratoconus and main control groups for all three SNPs: rs1536482 near the COL5A1 gene, rs2721051 near the FOXO1 gene, and the rs1324183 minor allele near the MPDZ gene." (PMID 34625056, 2021). "SNVs in the COL5A1 promoter do not play a major role in keratoconus susceptibility associated with rs1536482." (PMID 34625056, 2021). "Furthermore, LOX, FOXO1, FNDC3B, RXRA-COL5A1, MPDZ-NF1B, COL5A1 and ZNF469 are single-nucleotide polymorphisms (SNPs), exhibiting high risk of keratoconus." (PMID 28932340, 2017). "This meta-analysis identified six SNPs within or nearby FOXO1 (rs2721051), FNDC3B (rs4894535), RXRA-COL5A1 (rs1536482), MPDZ-NFIB (rs1324183), COL5A1 (rs7044529), and BANP-ZNF469 (rs9938149) genes/loci that were strongly associated with the risk of keratoconus." (PMID 25254113, 2014). "Using a similar approach Li and colleagues identified polymorphisms (rs1536482 and rs7044529) in the COL5A1 (OMIM 120215) region which regulate normal variation in CCT and may play a role in corneal thinning associated with keratoconus." (PMID 25254113, 2014). "Therefore, we conclude that rare SNVs in the COL5A1 promoter do not play a major role in keratoconus susceptibility associated with rs1536482." (PMID 34625056, 2021). "A recent study utilized whole exome sequencing (WES) to identify 34 keratoconus-related genes and noted genetic variation for several genes that are pertinent to EDS, including COL5A1, TNXB, ZNF469, and COL12A1." (PMID 37374145, 2023). "As for genetic factors, alterations in Lysyl oxidase (LOX), Collagen Type V Alpha 1 Chain (COL5A1), and Forkhead box protein O1 (FOXO1) gene have been correlated to keratoconus pathogenesis." (PMID 35054085, 2022). "This study aimed to investigate the replication of three SNPs (rs1536482 near the COL5A1 gene, rs2721051 near the FOXO1 gene, rs1324183 near the MPDZ gene) with keratoconus in the largest sample of patients from Russia." (PMID 34625056, 2021).
keratoconus (continued). "Additionally, we investigated the COL5A1 promoter sequence for single-nucleotide variants (SNVs) in a subgroup of keratoconus patients with at least one rs1536482 minor allele (rs1536482+) to assess the role of these SNVs in keratoconus susceptibility associated with rs1536482." (PMID 34625056, 2021). "Overall, we found a significant negative correlation of effect sizes across CCT and keratoconus (r = −0.62, P = 5.30 × 10−5), this correlation was largely unchanged if the known SNPs in ZNF469, FOXO1, COL5A1 and MPDZ/NFIB were removed from the analysis (r = −0.61, P = 2.04 × 10−4)." (PMID 29760442, 2018).
lung adenocarcinoma (15 papers, 2017 to 2025). A carcinoma that arises from the lung and is characterized by the presence of malignant glandular epithelial cells. "For instance, COL5A1 has been implicated in promoting mechanical stress and therapy resistance in lung adenocarcinoma, while COL11A1 activates CAFs through the TGF-β/NF-κB/IGFBP2 signaling axis in various solid tumors." (PMID 40574832, 2025). "COL5A1 encoded an alpha chain which was closely related to type XI collagen and was reported contributing to the metastasis of lung adenocarcinoma." (PMID 30723390, 2019). "For COL5A1, high expression is linked to increased risk in liver hepatocellular carcinoma (LIHC) and lung adenocarcinoma (LUAD) but offers protective benefits for KIRC, demonstrating its dual nature in cancer prognosis." (PMID 39635438, 2024). "However, when we knocked down COL5A1 in CAFs or treated them with Sorafenib, the invasive capacity of lung adenocarcinoma cells co-cultured with CAFs decreased compared with scrambled transfected CAFs." (PMID 38987529, 2024). "Among these, COL5A1 may be a new prognostic factor in patients with lung adenocarcinoma, and the miR-29b/COL5A1 axis can regulate bone metabolism and fibrosis response." (PMID 38398629, 2024). "In vitro experiments have shown that COL5A1 is related to lung adenocarcinoma metastasis and may play a role in tumor regulation, proliferation, and progression." (PMID 35152572, 2022). "Overexpression of COL5A1 may promote metastasis of lung adenocarcinoma and the progression of muscle-invasive bladder cancer and may increase the risk of hematogenous and lymphatic metastasis in serous ovarian cancer." (PMID 34777463, 2021). "Furthermore, in vitro experiment using siRNA knocking down the COL5A1 expression of myofibroblasts and co-culturing with lung adenocarcinoma cells, the Vimentin expression was downregulated, as well as the migration and invasion ability of lung adenocarcinoma cells." (PMID 38987529, 2024). "Moreover, COL5A1 may contribute the metastasis of lung adenocarcinoma." (PMID 32720739, 2020). "Therefore, multicolor immunofluorescence analysis was employed to investigate the relationship between COL5A1 and the tumor cell EMT pathway in the tissues of ten lung adenocarcinoma patients." (PMID 38987529, 2024).
ovarian carcinoma (15 papers, 2015 to 2025). A malignant neoplasm originating from the surface ovarian epithelium. "The elevated COL5A1 expression is associated with worse survival outcomes, thus COL5A1 is a potential biomarker predicting ovarian cancer progression and paclitaxel resistance." (PMID 38398629, 2024). "ALDH1A3, MARCKS, and COL5A1 were associated with reduced survival across all 3 datasets underscoring their relevance to ovarian cancer disease." (PMID 31534498, 2019). "In particular, THBS2, COL1A1, and COL5A1 genes are upregulated in most cancer types, except for bladder, kidney, melanoma, and ovarian cancer." (PMID 40860666, 2025). "This group demonstrated elevated expression of COL5A1 in ovarian cancer cells, while knockdown of this gene reduced cellular capabilities to proliferate and migrate." (PMID 38957320, 2024). "A knockdown of COL5A1 inhibits the proliferation and migration of ovarian cancer cells." (PMID 38398629, 2024). "COL5A1 is highly expressed in ovarian cancer cells and tissues." (PMID 38398629, 2024). "Furthermore, COL5A1 has recently been reported to be a key gene correlated with macrophage infiltration and M2 polarization and is related to the proportion of infiltrating immunocyte in ovarian cancer (OV), indicating that COL5A1 may be an immunotherapeutic target in OV." (PMID 35082969, 2022). "A previous study also showed that high expression of COL1A1, COL3A1, COL5A1, and COL5A2 in ovarian cancer promotes tumor immune tolerance and results in poor prognosis." (PMID 34034744, 2021). "The RT-qPCR results showed that compared with human ovarian epithelial cells, the expression of B3GAT3, COL5A1, FAM162A, IDUA, and PPP2R1A in ovarian cancer cells was significantly downregulated." (PMID 33281878, 2020). "We further analyzed the differential expression of B3GAT3, COL5A1, FAM162A, IDUA, and PPP2R1A in ovarian cancer SKOV-3 and A2780 cells and HOSEpiC human ovarian epithelial cells." (PMID 33281878, 2020). "It is worthy to note that some of the genes selected by the three methods (e.g., NPY, COL5A1, EGFR, and FBL1) have been already reported in literature where an analysis of subnetwork signatures in ovarian cancer based on Cox model is presented." (PMID 27378931, 2016). "In addition, transcriptomic analysis of the TCGA-ovarian cancer dataset revealed a positive correlation of ITGA2 expression to COL1A2, COL3A1, and COL5A1 involved in focal adhesion pathway." (PMID 33026975, 2020). "Furthermore, the enhanced expression of COL5A1, COL11A1, and VCAN through regulation of TGF-β1 signaling was identified in ovarian cancer metastasis." (PMID 33026975, 2020). "The expression of COL11A1, COL5A1 and COL6A2 is related to overall survival (OS) rate in patients with high-grade serous ovarian cancer, and their increased expression may also lead to the resistance of ovarian cancer cell lines." (PMID 36505882, 2022).
tendinopathy (15 papers, 2013 to 2025). "Single Nucleotide Polymorphisms of COL5A1 gene are reported to be involved in Achilles tendinopathy, chronic degenerative tendon changes at the elbow, and other tendinopathies." (PMID 32303186, 2020). "Although not all studies have reported an association, several have reported an independent association of the COL5A1 rs12722 CC genotype and/or C allele with a reduced risk (protective effect) of musculoskeletal soft tissue injuries, predominately tendinopathy." (PMID 36553626, 2022). "In addition, the MMP-3 rs679620 variant has been shown to interact with the COL5A1 rs12722 variant to modify the risk of tendinopathy." (PMID 29108328, 2017). "The main purpose of this study was to investigate how the functional polymorphisms within the COL5A1, COL27A1 and TNC genes impact the risk of developing tendinopathies in high-level Croatian athletes." (PMID 40869983, 2025). "On the other hand, the GG genotype of COL27A1 rs946053 suggested the protection of tendinopathies as well as the G-A-C haplotype constructed from COL5A1 rs12722, COL27A1 rs946053 and TNC rs2104772 T>A." (PMID 40869983, 2025). "The aim of this study was to investigate a possible association between the COL5A1 rs12722, COL27A1 rs946053 and TNC rs2104772 polymorphisms and tendinopathies in Croatian athletes." (PMID 40869983, 2025). "In the light of current knowledge, well-established factors of susceptibility to tendinopathy are the polymorphic variants of collagen, type I, alpha-1 (COL1A1), collagen, type V, alpha-1 (COL5A1) and matrix metalloproteinase 3 (MMP3) genes." (PMID 35743573, 2022). "The interest in COL5A1 gene raises from previous studies reporting on a correlation between different SNPs of such gene and tendinopathies." (PMID 32303186, 2020). "Our interest in SNP rs12722 of col5a1 gene raised from the significant correlation between such SNP and Achilles tendon tears or tendinopathy." (PMID 30572822, 2018). "Considering previous studies conducted on other populations, this study investigated further variations within COL5A1, COL27A1 and TNC genes and related risks of developing tendinopathies." (PMID 40869983, 2025).